CD47 (CD47 molecule)
Diseases named in the same sentence as CD47 in open-access papers (continued):
Sharing a sentence is not in itself a finding about the gene and the disease.
cancer (continued). "In vitro phagocytosis of cancer cells by human macrophages in the presence of a CD47 blocking monoclonal antibody (B6H12) and the survival of immunodeficient mice intraperitoneally engrafted with MKN45 cells and B6H12 were compared to experiments using control antibodies." (PMID 26077800, 2015). "Therefore, our data indicated that oncolytic adenoviruses carrying gene encoding sCAR-4N1 fusion protein is a novel strategy to redirect oncolytic adenoviruses to CD47+ cancer cells." (PMID 26554307, 2015). "Particularly, in vitro and in vivo studies have shown that macrophages are able to prime an effective CD8+ T cell response following anti-CD47 treatment-mediated phagocytosis of cancer cells, by concomitantly inducing a reduction in regulatory T cell population." (PMID 26578962, 2015). "Kim found that CD47 may play an inhibitory role in NK cell-mediated cytotoxicity against cancer cells, implying a possible mechanism of immune escape in human cancer." (PMID 25658794, 2015). "Collectively, these studies suggest that a humanized blocking anti-CD47 antibody may be an effective anti-cancer therapeutic both as monotherapy and in combinations." (PMID 26390038, 2015). "Similarly, elevated CD47 expression by some cancers protects them against natural killer (NK) cells, macrophage clearance, and antibody-dependent tumor cell killing." (PMID 26010544, 2015). "Hence, the targeted pSGNs conjugated withanti-CD47 antibodies are likely able to efficiently kill cancer cells in a direct photoablative manner." (PMID 26318039, 2015). "Cancer cells appear to upregulate CD47 as a mechanism of immune evasion." (PMID 26486085, 2015). "For high CD47-expressing cancer it may therefore be beneficial to include CD47-blocking therapeutics in order to optimize therapeutic efficacy." (PMID 25688334, 2015). "However, we are convinced that the selective inhibition of TSP-1 interaction with CD47 can induce a previously unpredicted overall anti-cancer response, to be explored and deciphered." (PMID 26046793, 2015). "An emerging anti-cancer therapy which shows promising results is the use of antibodies which block CD47, allowing for the immune system to recognize cancerous cells which previously exhibit large amounts of CD47." (PMID 25705515, 2014). "It has been recently demonstrated that anti-CD47 antibodies in mice model’s of myeloid leukemia and non-Hodgkin’s lymphoma were successful in eliminating the cancer cells without causing any damage to normal cells." (PMID 29147386, 2014). "Recent studies report aberrant expression of CD47 in several cancer entities." (PMID 25230070, 2014). "Furthermore, cancer cells abundantly express surface CD47, which is a negative regulator of phagocytosis and linked with cell survival/death." (PMID 41599693, 2026). "Supporting this notion, our investigations show that the αvβ3/CD47 interfering peptide PSFL‐NK13 disrupts the αvβ3/CD47–SIRPα axis without inducing the hemolytic side effects associated with CD47 antibodies, presenting a promising avenue for safe and effective cancer immunotherapy." (PMID 41168993, 2026). "Magrolimab, a first‐in‐class investigational monoclonal antibody against CD47 and macrophage checkpoint inhibitor is designed to interfere with recognition of CD47 by the SIRPα receptor on macrophages, thus blocking the “don't eat me” signal used by cancer cells." (PMID 41204420, 2026). "Interestingly, PD-L1 and CD47 are co-expressed in various cancers." (PMID 40861801, 2025). "Therefore, targeting innate checkpoint CD47-SIRRPα opens a new avenue for cancer immunotherapy." (PMID 40033359, 2025). "Additionally, immunofluorescence analysis showed that the combined CD47 antibody with rapamycin significantly increased the co‐localization of cancer cells with macrophages compared to rapamycin or CD47 antibody treatment alone, suggesting that this combination treatment promoted phagocytosis." (PMID 39665172, 2025).
cancer (continued). "Thus, Kupffer cells recognize and phagocytose cancer cells despite their expression of CD47." (PMID 40461700, 2025). "From the perspective of the “Cancer Cell Fusion” theory, a possible explanation for the favourable outcomes of CD47-SIRPα blockade is that CD47 on cancer cells may act as a trigger for macrophage-cancer cell fusion, mediated by the SIRPα marker on myeloid cells." (PMID 39967663, 2025). "Consequently, CD47 blockade represents a promising target for cancer therapy." (PMID 40380196, 2025). "Accordingly, the monoclonal antibody blockade against SIRPα could offer new treatment options for cancer by restoring macrophage-mediated phagocytosis without side effects associated with targeting CD47 directly." (PMID 40136470, 2025). "Moreover, the combination of anti-CD24 and anti-CD47 monoclonal antibodies was shown to remarkably promote the phagocytosis of cancer cells by macrophages, thus suggesting a plausible synergistic antitumor effect from two classes of phagocytosis checkpoint inhibitors." (PMID 40380196, 2025). "Moreover, as adaptive ICIs such as αPD-1/ αPD–L1 did not improve response rates in these patients, the combination with innate CD47 blockade using LicMAbs might synergize analogously with other cancer entities." (PMID 40402266, 2025). "Therefore, we propose that combining ferroptosis, the ICD effect, and CAT oxygen supply with CD47–SIRPα blockade may be an effective strategy for enhancing macrophage phagocytosis and improving cancer immunotherapy." (PMID 40051791, 2025). "In addition, CD47 is also crucial for cancer cells to evade immune clearance, and abolishing the binding of CD47 to SIRPα could induce target cell phagocytosis by macrophages." (PMID 38981064, 2024). "Furthermore, the dual blockade of CD47/SIRPα and PD-1/PD-L1 signaling, which respectively suppress innate and adaptive immune responses, has shown enhanced therapeutic efficacy in various cancer types, providing a promising avenue for cancer treatment that stimulates both arms of the immune system." (PMID 38475778, 2024). "Thus, CD47-blocking therapies may work best in combination with other therapies that make cancer cells more vulnerable to macrophage attack." (PMID 38483480, 2024). "The formation of complexes with CD47 and SIRPα transmits an antiphagocytic signal to macrophages, and the CD47-SIRPα pathway serves as an innate immune checkpoint to function as a druggable target, which enables cancer cells to escape from phagocytosis mediated by macrophages." (PMID 38177102, 2024). "Some of these CD47 signaling functions may be maintained or co-opted by malignant cancer cells." (PMID 38495618, 2024). "Therefore, combining anti-CD47 therapy with ICB therapies that target lymphocytes may lead to improved cancer treatment outcomes." (PMID 38261139, 2024). "ALKi might enhance anti-CD47-mediated phagocytosis thanks to the induced immunogenic cell damage, potentially in the off-target resistant setting as well, thus providing a further approach to definitely eliminate TKIs-resistant and persistent cancer cells." (PMID 39767726, 2024). "Furthermore, the effectiveness of the CD47-SIRPα signal relies on the phagocytic capabilities of macrophages, the predominant infiltrating cells in tumors, suggesting that directing attention to CD47 marks a pivotal development in cancer immunotherapy." (PMID 38543240, 2024). "In addition to targeting adaptive immune checkpoints for multiple metastatic and treatment-refractory cancers, recent studies have shown that innate immune checkpoint CD47 is critical for cancer cells to escape from immune surveillance such as macrophage attack and phagocytes." (PMID 39339173, 2024). "Moreover, the cancer cells presented with significant expression of CD47 protein on their surface." (PMID 38892394, 2024).
cancer (continued). "Although cancer cells tend to overexpress CD47, most normal cells, including hematopoietic cells, endothelial and epithelial cells, and fibroblasts (Human Protein Atlas), express CD47 as well, which may have resulted in the observed toxicity of magrolimab therapy." (PMID 38920727, 2024). "Anti-CD47 antibodies that block the interaction of CD47 with its ligand SIRPα, expressed on macrophages, have shown promising activity in preclinical cancer models by triggering cancer cell phagocytosis and enhancing adaptive immune responses against the cancer cells." (PMID 38690738, 2024). "Therefore, targeting CD47 likely represents a turning point in cancer immunotherapy." (PMID 36882399, 2023). "However, cancer cells express CD47 to avoid recognition by macrophages." (PMID 36768216, 2023). "Additionally, the “don’t eat me” signal, CD47, is upregulated in CSCs from several cancer types." (PMID 38164743, 2023). "Moreover, targeting stromal cells and combining CD47-targeted therapy with other targeted therapies such as tyrosine kinase inhibitors or PARP inhibitors may enhance its efficacy in specific cancer types." (PMID 38188674, 2023). "Therefore, targeting CD47 have emerged as an effective therapeutic strategy for cancer." (PMID 36810098, 2023). "Furthermore, recent studies have revealed that the combination of anti-PD1/PD-L1 and inhibition of CD47/SIRPα signaling developed more effective cancer immunotherapy through activating macrophages phagocytosis and antitumor effects which can further activate CD8+ T cells." (PMID 36845095, 2023). "Additionally, CD47 can be used as a prognostic marker in a variety of cancers." (PMID 36726125, 2023). "However, 2 major obstacles may delay the clinical translation of anti-CD47 antibodies in cancer immunotherapy." (PMID 36413402, 2023). "Importantly, CD47 blockade significantly enhances EGFR‐targeted cancer therapy in an animal model." (PMID 37541303, 2023). "Therefore, a potential ideal approach for cancer immunotherapy could involve inhibiting the interaction between SIRPα and CD47 while maintaining the binding between SIRPγ and CD47." (PMID 38125492, 2023). "From a translational perspective, the link between KRAS mutations and innate immune evasion suggests that targeting the KRAS/CD47 axis might compromise the ability of cancer cells to evade innate immune surveillance and increase their susceptibility to macrophage phagocytosis." (PMID 36413402, 2023). "However, how CD47 protein stability or degradation is controlled in cancer is still unclear." (PMID 36823443, 2023). "However, it is unclear whether the ERM family is involved in the cellular membrane localization of CD47 through post-translational modifications in cancer cells." (PMID 37189735, 2023). "In addition to CD47, cancer cells may upregulate other immune checkpoint molecules such as PD-L1, CTLA-4, LAG-3, and TIM-3 to evade immune surveillance and escape destruction by immune cells." (PMID 38188674, 2023). "Interestingly, the use of anti‐CD47 monoclonal antibody (mAb), in order to disrupt this checkpoint interaction between cancer cells and TAMs (also known as ‘don't eat me’ signal, DEMs), showed promising clinical activity in pretreated NHL, thanks to the increase in phagocytosis mediated by TAMs." (PMID 37654003, 2023). "As a result, CD47 could be a promising candidate for target therapy in future cancer treatments." (PMID 37373873, 2023). "Therefore, the CD47/SIRPA axis might also represent an interesting therapeutic candidate for these cancers." (PMID 36442992, 2023). "Importantly, we have demonstrated that the ERM family post-translationally regulate the cellular membrane localization of PD-L1, whose structure is similar to that of CD47, through molecular interactions, presumably by working as scaffold proteins in several cancer cell types, including PDAC." (PMID 37189735, 2023).
cancer (continued). "Furthermore, the high expression of CD47 in cancer cells suggested us that this could be a promising immune checkpoint." (PMID 37021054, 2023). "Importantly, CD47 blockade enhanced EGFR‐targeted cancer therapy." (PMID 37541303, 2023). "After being able to identify a subpopulation of cells with an increased stemness capacity, aggressiveness and migration capability, we further investigated whether these cells express CD47, needed by Circulating Cancer Stem Cells to evade from the immune system control." (PMID 38033871, 2023). "Therefore, THGP may increase the recognition of cancer cells and the phagocytic activity of macrophages against cancer cells by suppressing the expression of SIRP-α in macrophages and CD47 in cancer cells." (PMID 36768216, 2023). "Additionally, continued research is important for optimizing their efficacy and safety in different cancer types and patient populations, enhancing the efficacy of other cancer treatments, and reducing costs to make CD47-targeted therapy more accessible to patients." (PMID 38188674, 2023). "Therefore, increasing cancer cell phagocytosis by antagonising CD47 signalling with EVs may be an effective approach for cancer immunotherapy." (PMID 36298556, 2022). "Therefore, the combination of anti-CD47 with other immune checkpoint blockades or a combination of anti-CD47 with metabolism regulators could shed light on novel cancer treatment." (PMID 35697717, 2022). "Lastly, we enriched the functional pathways CD47 which may be involved in cancers." (PMID 35697717, 2022). "In recent years, multiple reagents targeting the CD47-SIRPα axis raised and showed a remarkable antitumor efficacy in multiple solid tumors, some of which were already at the phase I study, supporting the essential effect of regulating the CD47-SIRPα signal in cancer immunotherapy." (PMID 35422796, 2022). "Interestingly, some studies showed that blocking the CD47-SIRPα “don’t eat me signal” to promote macrophage phagocytosis of cancer cells may be ineffective in hypoxic colorectal cancer." (PMID 36071472, 2022). "We hypothesized that the SIRPγhi CSLCs may regulate CD47 expression in CSLCs and bulk cancer cell population through autocrine or paracrine signaling, particularly as previous studies revealed that cytokines such as TNF-α and IL-1β can stimulate CD47 expression." (PMID 35229723, 2022). "Treatment with CD47-CAR-T cells may be a novel strategy for treating different types of cancers." (PMID 35418166, 2022). "Moreover, since the expression of CD47 itself can be modulated in certain types of cancer upon therapy, this modulation of expression may offer opportunities for optimal combinatorial therapy design." (PMID 35908284, 2022). "Furthermore, SIRPα-EVs treatment promoted dense infiltration of T cells in a syngeneic cancer mouse model, raising the possibility that CD47-targeted therapy could unleash innate and adaptive antitumor responses." (PMID 36297672, 2022). "Thus, blocking the FAO-CD47 axis may eliminate the resistant cancer cells equipped with a boosted cellular energy fuel supply and CD47-mediated protection against macrophagic attack." (PMID 35314680, 2022). "Besides, inhibition of the Wnt signaling pathway in cancer cells could disrupt the expression of CD-47 and PD-L1, resulting in an increased immune defense against tumors." (PMID 37305016, 2022). "Similarly, CD47, which promotes immune evasion by engaging signal-regulatory protein alpha (SIRPα) and serves as an inhibitory receptor on macrophages, is emerging as a novel macrophage immune checkpoint for cancer immunotherapy." (PMID 35547750, 2022). "Therefore, we tested whether CRISPR-Cas9 mediated SIRPA gene knockout in monocytes can enhance ADCP and ADCC against a rituximab-opsonized CD47-expressing cancer cell line, i.e., Raji cells." (PMID 36077152, 2022).
cancer (continued). "Cancer cell membrane nanoparticles have the following distinctive characteristics: they cannot be easily removed; adhesion molecules on the membranes can promote the homologous targeting of cancer cells; and CD47 on the membrane of cancer cells prevents phagocytes from engulfing nanoparticles." (PMID 36559100, 2022). "Anti-CD47 treatment could be utiliezd as a promising strategy in a variety of cancers." (PMID 35697717, 2022). "Finally, microRNAs could negatively regulate CD47 gene expression in cancer cells by degrading messenger RNA or limiting translation." (PMID 35865547, 2022). "It has been suggested that antibodies may be ideally suited to this purpose as, in addition to blocking the CD47 axis, there will be an interaction between the antibody constant region and Fc receptors serving to further aid uptake of cancer cells by phagocytic cells." (PMID 34522209, 2021). "Thus, targeting CD47-SIRPα interactions promotes the functional reprogramming of macrophages towards an activated tumoricidal endotype and augments macrophage-mediated clearance of cancer cells." (PMID 34201127, 2021). "Modulation of CSCs markers, particularly CD47, directly by 4Mu or indirectly through the induction of M1 hepatic Mφ generated by 4Mu could be considered as an approach to sensitize cancer cells to TKI therapy, particularly in patients who have been previously treated with sorafenib." (PMID 33737571, 2021). "Therefore, a rational combination of SIRPα-CD47 axis blockade contributes to cancer immunotherapy." (PMID 34512146, 2021). "Besides, HIF-1 could regulate CD47 expression to promote evasion of phagocytosis and maintenance of cancer stem cells." (PMID 33754005, 2021). "In addition to block CD47/SIRPα checkpoint alone, combined SIRPα/CD47 with PD-1/PD-L1 blockade enhances the efficiency of antitumor immunotherapy 41, 47, 48, suggesting that SIRPα-CD47 axis blockade could enhance PD-1/PD-L1 blockade therapy for cancer." (PMID 34512146, 2021). "Therefore, CD47 should be regarded as a high-profile potential therapeutic target in cancer." (PMID 34093795, 2021). "Moreover, cancer cells have been described to avoid immune recognition by upregulating CD47." (PMID 34698067, 2021). "Thus, targeting the CD47-SIRPα axis, either through the CD47 or SIRPα blockade, may also promote antigen-presenting cell function, and stimulate T cell-mediated anti-cancer immunity." (PMID 34944850, 2021). "Hence, blockage of CD47 signaling could potentiate the therapeutic effects of anti‐angiogenic therapy in certain cancer." (PMID 34363319, 2021). "However, cancer cells can evade phagocytosis by upregulating anti-phagocytosis molecule CD47." (PMID 32198351, 2020). "The solution to this issue might lie in their combination with immune checkpoint blockade (ICB) therapy, which has gained prominence in recent years and demonstrated immense potential for cancer therapy, with anti-PD-1, anti-CTLA4, anti-CD47 now widely in use as anti-cancer agents." (PMID 32774773, 2020). "Additionally, anti‐CD47 antibody‐mediated phagocytosis of cancer cells has been shown to induce an antitumor T‐cell response via cross‐presentation of cancer cell antigens to the adaptive immune system, providing a second potential antitumor mechanism of action (MOA)." (PMID 32281289, 2020). "Interestingly, here we observed that the cell line MDA-MB-231 (TNBC) besides exhibiting a cancer stem cell-like (CD44high/CD24low) phenotype, is also positive for PD-L1 and CD47, two immune-related markers that can be further explored as new alternative target therapies." (PMID 32974189, 2020). "Thus, CD47 overexpression on cancers is a crucial survival mechanism." (PMID 32882841, 2020). "In addition to antibodies, the SIRPα/CD47 axis can be blocked by the use of recombinant SIRPα protein, whereby the exogenously added SIRPα protein interacts with endogenous CD47 on cancer cells, thereby preventing interaction with endogenous SIRPα expressed on phagocytes." (PMID 33105656, 2020).